CNR1 (cannabinoid receptor 1)
Diseases named in the same sentence as CNR1 in open-access papers (continued):
Sharing a sentence is not in itself a finding about the gene and the disease.
cancer (160 papers, 2008 to 2026). A tumor composed of atypical neoplastic, often pleomorphic cells that invade other tissues. "Depending on its binding to its corresponding ligands, CNR1 activates intracellular signaling pathways related to survival and is a potential biomarker of poor prognosis in cancer." (PMID 40302936, 2025). "THC has a binding affinity for cannabinoid receptor 1 (CB1), which has analgesic effects for neuropathic or cancer pain and an anti-emetic effect; however, it can also cause unwanted psychoactive effects." (PMID 40430155, 2025). "Simultaneously, LPS has been found to stimulate significant upregulation of the cannabinoid receptor 1 in the gastrointestinal tract, which promotes cancer cell proliferation." (PMID 38572314, 2024). "Research indicates that the deletion of cannabinoid receptor 1 can result in intestinal inflammation and cancer." (PMID 39336798, 2024). "Another study has validated the involvement of DNA methylation in suppressing CNR1 transcription in the same cancer type." (PMID 36291926, 2022). "On the other hand, hypomethylation of CNR1 in certain cancers leads to increased expression of CB1R, which may aid in tumorigenesis, pointing to the possibility that methylation modulates ECS tone across a number of diseases." (PMID 41303613, 2025). "In addition, several MMRs appear to have a distinct behavior in different cancer types, like CNR1, which is statistically significantly downregulated in 10 cancer types and upregulated in five, while HTR3A does the opposite." (PMID 39766077, 2024). "In 366 patients’ cases and the Cancer Cell Line Encyclopedia from Novartis and Broad Institute, which were analysed for mutations in CNR1, TRPV1 and PPARα, up to 3% were mutated (with no mutational hotspot)." (PMID 37237519, 2023). "Evidence suggests that endocannabinoids might suppress cancer cell viability through the activation of classic cannabinoid receptors such as cannabinoid receptor-1/2 (CB1 and CB2) and vanilloid receptor-1 (VR1)." (PMID 27411387, 2016). "Specifically, ACEA can activate cannabinoid receptor 1 (CB1) and alter tumor microenvironment; concurrently, ROS produced by the MSs directly injures cancer cells, which together induces immunogenic tumor cell death." (PMID 38350727, 2024). "Among them, several up-regulated genes are known to be involved in the formation of tumor microenvironments (Carbonic anhydrase 2 (CA2)), cancer chemoresistance (Cannabinoid receptor 1 (CNR1), GFRA1) and cancer recurrence after therapy (RGL3)." (PMID 36769365, 2023). "MGMT and CNR1 are two classical markers for the CpG island methylator phenotype (CIMP) and they are hypermethylated in cancers." (PMID 31534549, 2019). "We therefore examined the mRNA expression of seven cannabimimetic receptors – CNR1 (CB1), CNR2 (CB2), GPR55, TRPV1, TRPV2, TRPA1, TRPM8 – and found them to be differentially expressed amongst the 12 tested cancer cell lines." (PMID 31289609, 2019). "CNR1, DHCR24, DPP6, and MEF2C were strongly correlated with disturbances in executive functioning, episodic memory, and visuospatial functioning, which deregulate expression in multiple human cancers contributing to the antioxidant and repairing activity." (PMID 36518809, 2022). "Although it is known that the relationship between CB receptors and the anti-cancer effect of CBD has been uncertain, it was reported that CBD downregulated the CB1 receptor level through the low expression of CNR1 and could reduce the viability of MCF7 cells." (PMID 34830821, 2021). "Carcinoma genome-wide methylation screening revealed that methylation of CNR1 was correlated with MYCN amplification, and patients with low mRNA expression levels of CNR1 had a poor prognosis." (PMID 34745201, 2021).
tumor (152 papers, 2006 to 2025). "A similar observation was found in another study in which exposure to prostaglandin E2 suppressed CNR1 gene expression by increasing DNA methylation in the CNR1 promoter region in the human epithelial colon cell line LS-174T, causing tumor growth." (PMID 36358910, 2022). "The type 1 cannabinoid receptor (CB1) is a tumor suppressor encoded by CNR1 with antiproliferative and proapoptotic activity in CRC cells." (PMID 29259973, 2017). "The cannabinoid receptors 1 and 2 (CNR1&2) are overexpressed in a variety of malignant diseases and cannabinoids can have noteworthy impact on tumor cell viability and tumor growth." (PMID 27248492, 2016). "Moreover, the combined use of CNR1 antagonists and ferroptosis inducers has demonstrated good anti-tumor effects in TNBC." (PMID 40302936, 2025). "Signaling through CNR1 might thus be involved in regulating the retention of MCL cells in lymphoid tissue a niche that provides optimal conditions for tumor cell growth and survival and potentially enhanced resistance to many therapeutic agents." (PMID 25594062, 2014). "Meanwhile, CNR1 might be an important tumor promoter in HCC." (PMID 31346321, 2019). "Aberrant expression of components of the endocannabinoid system, especially CNR1 and CNR2, seems to be related to tumour growth and progression." (PMID 35008410, 2022). "For the targets for AEA and 2-AG, Cnr1 levels were lower and Cnr2 levels higher in the tumour tissue than in the HC tissue, and the Cnr2 levels higher in the AT1 tumour than the MLL tumour." (PMID 32286386, 2020). "The tumour tissue shows increased Dagla and Cnr2 levels and reduced Cnr1 and Faah levels compared to the HC tissue; the AT1 tumours show increased Naaa levels and the MLL tumours show increased Napepld levels." (PMID 32286386, 2020). "In GC cells, PGE2 induced DNMT3B expression and activity, leading to increased methylated cytosine (5mC) and promoter methylation of tumor suppressive genes (MGMT and CNR1)." (PMID 31534549, 2019). "The same study reported an antiapoptotic role for CNR1 in cHL and hypothesized that CB receptors function as a survival factor for HRS cells and concluded that endocannabinoid system activation promotes tumour cell growth." (PMID 35008410, 2022). "The lack of change for Faah and Cnr1 in the TINT seen here is reminiscent of the situation in PCa patients, where tumour, but not TINT FAAH and CB1 receptor immunoreactivity is associated with disease severity and outcome." (PMID 32286386, 2020). "The expression levels of CNR1, CNR2 and FAAH did not correlate to the tumor cell content in the tissue as measured by flow cytometry." (PMID 25594062, 2014).
metabolic disorders (57 papers, 2010 to 2026). "Several genetic studies have been performed to link CNR1 mutations to psychiatric but also metabolic disorders." (PMID 24662753, 2014). "Over-activation of cannabinoid receptor 1 (CB1R) in adipose tissue is proposed in the pathophysiology of metabolic disorders, which led to the metabolic dysfunction of adipose tissue and deregulated production and secretion of adipokines." (PMID 29731737, 2018).
psychiatric disorder (17 papers, 2016 to 2024). A disorder characterized by behavioral and/or psychological abnormalities, often accompanied by physical symptoms. "Our results suggest that allelic variation in the CNR1 gene is associated with differential gene expression, leading to differential vulnerability towards the development of psychiatric disorders." (PMID 32433545, 2020). "Given that the CNR1 gene has been implicated in the pathology of a wide range of psychiatric disorders, examining its effects on personality traits is of great interest, as they are regarded as risk factors for these disorders." (PMID 29963071, 2018). "Considering that variants in CNR1 have been reported to be associated with an increased risk of mental health conditions, these data indicate the presence of genetic influences shared by personality traits and psychiatric disorders." (PMID 29963071, 2018). "Therefore, we hypothesized that CNR1 variants could also contribute to the disease complexity predisposing the patients to psychiatric comorbidities as all the CNR1 polymorphisms studied here had been found to be associated with various psychiatric disorders." (PMID 32194619, 2020). "These adverse effects, mainly produced by cannabinoid receptor 1 (CB1r) activation, must be considered in treating psychiatric disorders." (PMID 35563156, 2022). "Dysfunction of CNR1 may result in neuropsychological disturbances, leading to psychiatric disorders." (PMID 29963071, 2018). "In PTSD patients, the Cnr1 gene was one of several uniquely methylated genes found in patient’s PBMC, suggesting variations in CB1 expression could be involved in the pathology of this disease, as well as other psychiatric diseases, as discussed in previous reviews." (PMID 37520658, 2023).
neurological disorders (16 papers, 2017 to 2025). "CNR1 and the endocannabinoid system were previously identified as potential targets for treatment of neurological disorders and AD in particular." (PMID 30021611, 2018). "Rare genetic variants in the core endocannabinoid system genes CNR1, CNR2, DAGLA, MGLL and FAAH were identified in molecular testing data from 6,032 patients with a broad spectrum of neurological disorders." (PMID 29145497, 2017). "This is exemplified by the severe neurological disorder that occurred during a phase I trial of the fatty acid amide hydrolase (FAAH) inhibitor BIA 10-2474 and the psychiatric side effects associated with the cannabinoid receptor 1 (CB1) inverse agonist rimonabant." (PMID 39673602, 2025). "It should also be noted that rare genetic variations in ECS, including the genes CNR1 and CNR2 encoding CB1R and CB2R, respectively, as well as the genes for the degrading enzymes DAGLA, MGLL, and FAAH have been reported in patients with neurological disorders." (PMID 39796008, 2024).
infection (14 papers, 2010 to 2026). The state of being infected such as from the introduction of a foreign agent such as serum, vaccine, antigenic substance or organism. "Furthermore, infection of HINT1-/- neurons with HINT1 lentiviral particles increased HINT1 expression, which resulted in the co-precipitation of CNR1 with the NR1 subunits." (PMID 24093505, 2013). "Interestingly, Cnr1-/- mice showed enhanced microglial reactivity and VCAM-1 expression following TMEV infection, indicating that the lack of CB1 receptor exacerbated neuroinflammation." (PMID 21851608, 2011).
cardiovascular disease (13 papers, 2013 to 2026). "Rimonabant, a cannabinoid receptor-1 (CB1) antagonist, shows promise in cardiovascular disease prevention." (PMID 38686376, 2024). "RNA expression data from atherosclerotic plaque tissue and nonatherosclerotic tissue samples from patients with cardiovascular disease were extracted, and the expression of CNR1 was greater in atherosclerotic tissues than in nonatherosclerotic tissues." (PMID 41559687, 2026). "Cannabinoid receptor 1 (CB1R), a G protein‐coupled receptor (GPCR), is widely expressed in the central nervous system (CNS) and peripheral organs and has been found to be upregulated in various cardiovascular disease states and may influence disease progression." (PMID 40976942, 2025).
inflammation (10 papers, 2013 to 2023). Aberrant reaction of the microcirculation characterized by movement of fluid and leukocytes from the blood into extravascular tissues. "The levels expression of 21 genes, including ADRA2B, CNR1 and LEP were significantly altered in the gastric tissue of NAFLD patients with hepatic inflammation." (PMID 24716593, 2014). "In agreement with our findings, a previous study found that miR-30b-5p was participated in cannabinoid receptor 1-mediated activation of NLRP3 inflammasome in macrophages, and miR-30b-5p agomir decreased the expression of NLRP3, thereby attenuating liver inflammation." (PMID 35500231, 2022).
neurodevelopmental disorder (4 papers, 2021 to 2025). A behavioral and cognitive disorder with onset during the developmental period that involves impaired or aberrant development of intellectual, motor, or social functions. "In conclusion, our results add to previous evidence implicating the endocannabinoid system with neurodevelopmental disorders, such as SSD, and represent new evidence regarding the CNR1 gene in the development and variability of dermatoglyphic patterns." (PMID 39457583, 2024).
bacterial infection (2 papers, 2021 to 2025). "The activation of cannabinoid receptor 1 (CB1) is essential for the development of an effective innate immune response during bacterial infection." (PMID 33477901, 2021).
CNR1 also shares sentences with these, for which no sentence is quoted: neurodegenerative disease (31 papers); Alzheimer disease (30); prostate carcinoma (28); Stroke (23); Glucose intolerance (16); Hyperglycemia (16); lung carcinoma (15); multiple sclerosis (15); osteoarthritis (14); post-traumatic stress disorder (13); Parkinsonism (12); Cerebral ischemia (11); pancreatic cancer (11); cardiomyopathy (10); non-alcoholic fatty liver disease (10); Arthritis (9); chronic kidney disease (9); eating disorder (9); leukemia (9); osteoporosis (9); astrocytoma (8); Dyskinesia (8); endothelial dysfunction (8); glaucoma (8); liver cirrhosis (8); temporal lobe epilepsy (8); cognitive decline (7); Headache (7); Hyperinsulinemia (7); myocardial infarction (7).
A further 303 diseases each share a sentence with CNR1 in 7 papers or fewer.